ULK1 (unc-51 like autophagy activating kinase 1)
Diseases named in the same sentence as ULK1 in open-access papers (continued):
Sharing a sentence is not in itself a finding about the gene and the disease.
tumor (continued). "As for ULK1, it has been well-studied as a key initiator of autophagy, a self-digestion process for recycling cellular fuel, producing bioenergy and inducing cell death and is therefore believed to be a potent tumor suppressor." (PMID 32580279, 2020). "Both the inhibition and activation of ULK1 have significant effects on tumor therapy." (PMID 32033142, 2020). "Here, we investigate novel roles of NEDD4L in modulating autophagy activity and mitochondrial metabolism on contributing to tumor progression by which regulates the protein levels of an autophagy protein, ULK1, and ASCT2, a transporter of glutamine that is a substrate for mitochondrial anaplerosis." (PMID 31959741, 2020). "Indicating that AMPK/ULK1 pathway may important to anti-tumor drugs to induce autophagy for targeting cancer therapy in the future." (PMID 31871431, 2019). "For example, the synergistic effect of targeting mTOR with a combination of everolimus and another new-generation phosphatidylinositol 3-kinase/mTOR adenosine triphosphate-site competitive inhibitor BEZ235 or with the ULK1 inhibitor suppresses proliferation of tumor cells." (PMID 29643976, 2018). "Finally, ULK1 activation is abrogated in tumor-bearing mice with muscle-specific knockout of p38β MAPK." (PMID 31225455, 2018). "Moreover, Beclin-1 and ATG7, which act downstream of ULK1, were also significantly upregulated in tumor tissues compared with the corresponding background tissues." (PMID 28079894, 2017). "In addition, further correlation analysis demonstrated that high expression of ULK1 in NPC was positively correlated with tumor aggressive and advanced clinical stage." (PMID 25714809, 2015). "Our study demonstrated that ULK1 was an independent prognostic biomarker for therapeutic response in NPC, and examination of ULK1 expression by IHC method might be helpful in determining the prognosis of this tumor in clinical practice." (PMID 25714809, 2015). "Additionally, the stable knockdown of ULK1 also led to a decrease in tumor weight." (PMID 38286802, 2024). "Hence, we tested whether DCC-3116-mediated inhibition of ULK1/2, starting at tumor initiation in KL mice, would inhibit tumor growth." (PMID 39213022, 2024). "Therefore, ULK1 seems to have a minimal impact on tumor cell proliferation." (PMID 39215364, 2024). "Therefore, we speculate that miR-214 may initiate ULK1 mediated autophagy through downregulation of expression after chemotherapy, resulting in further death of tumor cells." (PMID 35692501, 2022). "In addition, BECN1 and ULK1 have been shown to promote tumor growth in various cancers." (PMID 36177001, 2022). "Therefore, ULK1 activity may contribute to the survival of tumor cells under the conditions of NUAK1 inhibition and oxidative stress." (PMID 32873786, 2020). "Therefore, we applied HCQ or SBI-0206965 (ULK1 inhibitor) to NNMT KD tumors in the mouse model, assuming that an autophagy inhibitor could offset the beneficial effect of NNMT KD on tumor cells under nutrient-deficient conditions." (PMID 30093610, 2018). "Previous studies have revealed several abnormally expressed genes in NPC that could serve as reliable prognostic factors, like H3K27me3, ULK1, LOX, Talin-1 and PTP4A3, however, the existing molecular markers are substantially limited in identifying tumor spread and aiding risk assessment." (PMID 29100406, 2017). "Pharmacological ULK1 activation with LYN-1604 restores sunitinib sensitivity in PDZK1-knockdown cells and synergizes with sunitinib in xenograft models, reducing tumor growth and LD accumulation." (PMID 41698049, 2026). "Cytokine and chemokine profiling of CM from Ulk1 WT and Ulk1 KO KPC cells revealed distinct secretory profiles, reinforcing the tumor-promoting immune landscapes." (PMID 41408407, 2025).
tumor (continued). "Collectively, these data demonstrate that Ulk1 is critical for PDAC progression in a physiologically relevant spontaneous PDAC model and support its function as a key effector of both primary tumor growth and metastatic potential." (PMID 41408407, 2025). "These tumor-intrinsic cytokine changes were recapitulated in vitro using CM from Ulk1 KO KPC cells, confirming that Ulk1-mediated tumor signaling influences immune cell recruitment as determined by the types of cytokine and chemokine." (PMID 41408407, 2025). "The promotion of autophagy, BC cells proliferation, and tumor growth is facilitated by the interaction between circCDYL and miR-1275 targeting the ATG7/ULK1 axis." (PMID 39281375, 2024). "Both in cell line- and patient-derived xenograft models, combining a ULK1/2 inhibitor and a KRAS G12C inhibitor rendered higher efficacy in tumor control." (PMID 38756650, 2024). "The western blotting results of tumor tissue proteins suggested that ICA also increased the phosphorylation of AMPK and ULK1 while reducing the expression of phosphorylated mTOR protein in vivo." (PMID 38355608, 2024). "GZ17-6.02 interacted with bortezomib to enhance autophagosome formation and autophagic flux, and knock down of ATM, AMPKα, ULK1, Beclin1 or ATG5 significantly reduced both autophagy and tumor cell killing." (PMID 38441437, 2024). "Simultaneously, we performed a parallel analysis of the levels of p-AMPK, p-mTOR, p-ULK1, and BMF in tumor tissues via Western blotting." (PMID 39598428, 2024). "Previous studies have shown that UNC-51-like kinase 1 (ULK1), a serine/threonine kinase, is crucial in regulating cellular autophagy and mitophagy across various tumor types." (PMID 38286802, 2024). "The expression of chemoresistance genes has been detected, including KLF4 (doxorubicin and ifosfamide), ULK1, LUM, GPNMB, and CAVIN1 (doxorubicin), and AHNAK2 (gemcitabine) in tumor cells and ETS1 (gemcitabine) in TME." (PMID 39685635, 2024). "Unc-51-like kinase 1 (ULK1) is also related to autophagy and can either promote or inhibit tumor growth." (PMID 38234672, 2024). "Caprin-1 activated autophagy through the interaction with ULK1 and STK38 that promoted tumor growth." (PMID 38082307, 2023). "Other autophagy modulators, such as VPS34, ULK1, and ATG4B inhibitors have been confirmed to exert tumor suppressor effect in clinical mouse models." (PMID 36900050, 2023). "Here, JQ1 significantly inhibited tumor growth and induced autophagic flux, as indicated by elevated levels of LC3II and p-ULK1, as well as p62/SQSTM1 degradation." (PMID 37628849, 2023). "Next, patients were separated into Caprin-1High and Caprin-1Low subgroups according to average expressions of Carpin-1 in tumor, the effects of STK38 and ULK1 on evaluating OS were explored in Caprin-1High patients." (PMID 38082307, 2023). "There is also evidence that drugs targeting autophagy regulators in other stages of autophagy, such as ULK1/2, VPS34 and ATG4B, can have anti‐tumour effects." (PMID 37837401, 2023). "They upregulate tumour cell viability and autophagy and inhibit apoptosis through the LUCAT1/miR‐514a‐3p/ULK1 axis and PVT1/miR‐216b‐5p/Beclin 1 axis, respectively." (PMID 37837401, 2023). "However, when miR-214 is overexpressed, it could antagonize the inhibitory effect of ULK1 on tumor." (PMID 35692501, 2022). "It showed that when ULK1 was low expressed during chemotherapy, the autophagy activity in CAL-27 was greatly inhibited, while the activity of tumor cells increased significantly." (PMID 35692501, 2022).
tumor (continued). "Although BNIP3 is a potential target of ULK1, decreased BNIP3 protein levels in STAT3‐KO and mutant expressing cells indicate that BNIP3 is degraded by ULK1‐dependent autophagy, a mechanism found to decrease BNIP3 protein levels in tumour cells." (PMID 35670018, 2022). "In esophageal squamous carcinoma, CLDN1 was revealed to promote tumor development and invasion via autophagy activation through the 5′AMP-activated protein kinase/STAT1/Unc-51 like autophagy activating kinase (ULK1) signaling pathway." (PMID 36193204, 2022). "For example, NEDD4L prevents autophagy activity under metabolic stress by destabilizing ULK1, an autophagy protein, and ASCT2, a glutamine transporter, hence reducing mitochondrial functioning and tumor suppression." (PMID 36293239, 2022). "Notably, compared to tumor cell types we have previously treated with neratinib as a single agent, we observed a profound increase in the phosphorylation of ULK1 S317 and profound reductions in the phosphorylation of ULK1 S757, mTORC1 S2448, mTORC2 S2481 and p70 S6K T389." (PMID 36227739, 2022). "Alongside ULK1 activators, Martin and colleagues identified two ULK1 small-molecule inhibitors, ULK-100 and ULK-101, which can disrupt autophagy, making tumor cells more sensitive to nutrient depletion." (PMID 36291728, 2022). "Knock down of ULK1, ATG5 or Beclin1 significantly reduced tumor cell killing by the drug combination." (PMID 33898322, 2021). "ULK1/2 is positively correlated with YAP and PKM2 in tumor tissues from KPC mice and clinical samples from PDAC patients." (PMID 34345207, 2021). "For example, long non-coding RNA PVT1 is reported to be closely related to autophagy and has been proved to affect tumor autophagy via miR-365/ATG3, miR-20a-5p/ULK1, miR-619-5p/ATG14 or multiple axes." (PMID 34823534, 2021). "ULK1/2 is a known inhibitor of BCL2/adenovirus E1B 19 kDa interacting protein 3 (BNIP3) 27, the atypical BH3-only protein which functions as a tumor suppressor in human cancers 28-30." (PMID 34345207, 2021). "Herein, we investigated the mechanisms by which ULK1 is modulated by an E3 ubiquitin ligase, NEDD4L, and suggest the physiological significance of these molecular regulations on tumor progression." (PMID 31959741, 2020). "Here, the authors report Exo70 as a substrate of ULK1 that suppresses cancer metastasis, and show that ERK1/2 mediated phosphorylation of Exo70 leads to opposing effects on tumour cell invasion." (PMID 31913283, 2020). "The novelty of our study resides in the demonstration that the PI3K/mTOR inhibitor NVP-BEZ235 induces autophagy by AMPK/ULK1 pathway and the combinational treatment of NVP-BEZ235 and CQ further promote apoptosis to suppress tumor growth." (PMID 31871431, 2019). "Activated ULK1 forms a complex with p38β MAPK in myocytes, which is markedly increased by a tumor burden." (PMID 31225455, 2018). "The mentioned miRNAs can also increase the expression of autophagy genes including ULK1, ATG7, or p62, trigger autophagy, and suppress HCC tumor growth." (PMID 29643976, 2018). "Subsequent analysis of LKB1−/− NSCLC tumour lines revealed inactivation of the AMPK-ULK1 signalling thus phenocopying the mitochondrial defects and reduced autophagy observed in Ampk−/− and Ulk1−/− murine embryonic fibroblasts." (PMID 26196184, 2015). "The results showed that ISL with or without epirubicin significantly inhibited miR-25 expression in the tumor tissue; this was accompanied by increases in the expression of LC3-II, ULK1 and BECN1 as well as a decrease in the expression of ABCG2." (PMID 25026296, 2014).
tumor (continued). "To further assess whether tumor-intrinsic Ulk1 deletion affects immune cell composition in vivo, we used syngeneic orthotopic models by injecting KPC sgSC (Ulk1 WT) and KPC sgUlk1 (Ulk1 KO) cells into the pancreas of immunocompetent C57BL/6J mice." (PMID 41408407, 2025). "In addition, copper regulates tumor cell autophagy by affecting the activity of the autophagy kinases ULK1 and ULK2 (ULK1/2)." (PMID 40164592, 2025). "In vivo, tumor growth was inhibited following USP10 knockdown, with lower tumor weights and volumes were observed in the shUSP10 group compared to the shNC or shUSP10 + ULK1 groups." (PMID 39218913, 2024). "In our study, the introduction of chrysin did not alter the expression of mTOR in tumor cells; conversely, it inhibited the phosphorylation of ULK1, effectively reversing the autophagic activation state in the cells." (PMID 38675475, 2024). "Moreover, prostate adenocarcinoma patients from the TCGA dataset displaying a tumour mRNA expression level greater than 2-fold above the mean of either ATG4B, ATG4D, ULK1, or ULK2, had poor prognosis." (PMID 38910881, 2024). "Our data demonstrated that autophagosome formation and MM cell killing by the drug combination was most effectively reduced by knocking down the expression of ULK1, Beclin1 or ATG5, strongly arguing that macroautophagy played a key role in tumor cell execution." (PMID 38441437, 2024). "Furthermore, the total levels of ULK1 and its phosphorylation by AMPK at Ser555 were documented upon the knockdown of Hsp70 or HSF1 in A549 tumor cells." (PMID 39201776, 2024). "The upregulation of the ULK1 gene evidenced a mechanism of ROS-induced cell death in HCT116 and DU145 cells, but antioxidant genes were as well overexpressed, suggesting that these tumor cells attempted to counteract the oxidative damages induced by 64Cu." (PMID 37415761, 2023). "Finally, to further determine the role of IPMK and the AMPK/ULK1 pathway in ebastine-mediated antitumor activity in vivo, we examined expression of IPMK and the AMPK/ULK1 pathway in subcutaneous tumor tissues." (PMID 36632464, 2023). "Our findings indicate an antagonistic role of Leon/USP5 in Atg1/ULK1-mediated autophagy and may provide mechanistic insights into how USP5 promoted tumor growth and progression." (PMID 37607937, 2023). "In addition, the silent expression of miR-214 negatively regulated ULK1 level, thereby increasing autophagy activity in CAL-27 cells, leading to tumor cell apoptosis and inhibiting distant metastasis." (PMID 35692501, 2022). "This includes the tumor suppressor LKB1, AMPKα1, ULK1, Atg14 and Beclin-1." (PMID 36578014, 2022). "The confirmation of ULK1’s immune suppressive function suggested that our CRISPRa screening used the coculture system of CD8+ T cells, and tumor cells could successfully identify the established immune regulator." (PMID 36475797, 2022). "In addition, autophagy activates ULK1 (unc-51 like autophagy activating kinase 1) and MAPK/JNK, which are essential for macrophage production and inhibition of tumor progression." (PMID 36497321, 2022). "Moreover, the result of Western blots showed that the expressions of SDHB and CCS were downregulated and that of ULK1, CDKN2A, and CMC1 were upregulated in tumor tissues compared with normal tissues." (PMID 36505872, 2022). "Moreover, the generation of a specific ULK1 inhibitor XST-14 and used in combination with Sorafenib significantly reduces HepG2 tumor growth." (PMID 34829868, 2021). "Interestingly, apart from its inhibitory effect toward ULK1, SBI-0206965 also blocks the activity of AMPK, and, when combined with MTOR, the inhibitors greatly increase the cell death of tumor cells." (PMID 34830777, 2021). "In addition, our data show that ULK1/2 expression are positively correlated with YAP and PKM2 levels in tumor tissues from KPC mice and samples from clinical patients with PDAC." (PMID 34345207, 2021).
tumor (continued). "Interestingly, the levels of either ULK1 or LC3B increased, as the intensity of NEDD4L staining decreased in the same tumor regions." (PMID 31959741, 2020). "Decreased expression of Beclin1 along with a reduced level of LC3-II as well as a relative decline in ULK1 and TFEB1 mRNA levels resulted in enhanced chemotherapy, mitigated drug resistance, and tumor growth inhibition on the cisplatin-resistant tumor in xenograft mouse model." (PMID 31557936, 2019). "In the present study we show that despite AMPK activation by LLC in skeletal muscle, AMPK does not mediate in ULK1 activation LLC tumor-bearing mice." (PMID 31225455, 2018). "Our findings demonstrate for the first time that miR-26a/b can promote apoptosis and sensitize HCC to chemotherapy via suppressing the expression of autophagy initiator ULK1, and provide the reduction of miR-26a/b in HCC as a novel mechanism of tumor chemoresistance." (PMID 28079894, 2017). "We show that the G116A mutation impaired GABARAPL1 function in autophagosome/lysosome fusion and inhibited lysosome activity but did not alter MTOR and ULK1 activities or tumor growth in vivo." (PMID 28915569, 2017). "Our findings reveal that tumor-intrinsic ULK1 deletion suppresses PDAC progression by impairing autophagy-mediated tumor adaptation and by reprogramming the tumor microenvironment (TME) through altered infiltration of distinct immune cell subtypes, thereby providing tumor-suppressive immune states." (PMID 41408407, 2025). "Interestingly, the messenger RNA level of ULK1 was not significantly different between tumor and normal tissues." (PMID 41408407, 2025). "However, the specific mechanism governing ULK1 expression in EOC and its subsequent pro-tumor effect remains unclear." (PMID 38286802, 2024). "To mimic the physiological and pathological states of human PTC, we established PTC tumor-bearing mouse models using PTC cell lines with NC (normal control), sh-AdipoR1 (AdipoR1 gene silencing), sh-AdipoR2 (AdipoR2 gene silencing), and sh-ULK1 (ULK1 gene silencing)." (PMID 39349421, 2024). "In addition, following PKM2 knockdown and overexpression, the expression levels of p-AMPK, p-mTOR, p-ULK1, and p-4E-BP1 proteins in Ad-apoptin treated tumor cells were analyzed by western blot to investigate the mechanism of apoptin effect on the energy metabolism of tumor cells." (PMID 36284386, 2022). "Pharmacological deactivation of ULK1/2 using a small-molecule kinase inhibitor SBI-0206965 synergizes with hexokinase I inhibitor 2-deoxyglucose (2-DG) and hexokinase II inhibitor 3-bromopyruvate (3-BP) to suppress tumor development in both PDAC cell- and patient-derived xenograft models." (PMID 34345207, 2021). "Furthermore, 30 clinical specimens were tested and the level of miR-26a/b in tumor tissues was lower than that in para-carcinoma tissues, and only negatively correlated with the level of ULK1 protein, but not with the change of ULK1 mRNA level." (PMID 33712559, 2021). "Besides, we analyzed the expression levels of mRNA ULK1, proposed as a direct target of miR-106a, and found no significant changes of ULK1 in HCT116 similarly to the non-tumor cell line." (PMID 33572255, 2021). "Since Ulk1, Vps34, and Atg7 represent the key nodes of the autophagy pathway, these results indicate that the effects of Ppt1 inhibitors are independent of the autophagy pathway in tumor cells at least in the B16 model." (PMID 32780726, 2020). "It was shown that, under metabolic stress, ULK1 phosphorylates the focal adhesion kinase (FAK) family interacting protein of 200 kDa (FIP200), which subsequently leads to the inhibition of FAK-directed tumor cell motility and metastasis in non-small cell lung cancer." (PMID 31913283, 2020). "Moreover, upon blocking copper binding to ULK1 (by replacing endogenous ULK1 by a mutant form lacking the copper binding site), tumor growth kinetics are reduced, resulting in significantly lower tumor weight in a xenograft model." (PMID 32420529, 2020).